MEX3A (mex-3 RNA binding family member A)
Diseases named in the same sentence as MEX3A in open-access papers (continued):
Sharing a sentence is not in itself a finding about the gene and the disease.
tumor (continued). "In this study, we found that MEX3A was significantly upregulated in tumor tissues of ESCC, which was also verified in ESCC cell lines." (PMID 33188661, 2020). "Meanwhile, MEX3A overexpression exhibited conversed effects against MEX3A knockdown, emphasizing the role of MEX3A in ESCC as a tumor promotor." (PMID 33188661, 2020). "This study showed that MEX3A expression is significantly upregulated in PDA and associated with tumor grade." (PMID 32140076, 2020). "The intestine has a reservoir of quiescent stem cells that are resistant to chemotherapy that are marked by Mex3a and are multipotent so have the capacity to produce any kind of intestinal cell and contribute to tumour heterogeneity." (PMID 32909943, 2020). "In this study, we found that MEX3A was upregulated in tumor tissues of ESCC and positively associated with more advanced tumor stage, higher risk of lymphatic metastasis and poor prognosis." (PMID 33188661, 2020). "Consistently, the gene expression profiling data collected from The Cancer Genome Atlas (TCGA) also showed the upregulation of MEX3A in ESCC tumor tissues (Fold change 4.07, P < 0.001)." (PMID 33188661, 2020). "We performed tail vein injection with Mex3a-knockdown H1299 cells to establish tumor metastasis mouse models." (PMID 32792503, 2020). "In this study, it was found that MEX3A is not only highly expressed in tumor tissues and human cultured cells of PDA, but also significantly correlated with patients’ prognosis." (PMID 32140076, 2020). "The results of the independent t-test of 19 paired samples indicated that the expression level of mex3a was significantly higher in tumor tissues compared with adjacent normal tissues." (PMID 28903380, 2017). "The result of the independent sample t-test indicated that the level of mex3a expression was significantly higher in tumor tissues compared with adjacent normal tissues (P=0.008)." (PMID 28903380, 2017). "These MEX3A+ cells, initially characterized by reduced proliferation, metabolic downregulation, and distinct transcriptional signatures, persist through chemotherapy and later regenerate the tumor mass." (PMID 41002429, 2025). "Furthermore, upon the IDRs deletion, the increased subcutaneous tumor growth by MEX3A overexpression was attenuated." (PMID 38565536, 2024). "Importantly, tumor xenograft assay showed that MEX3A knockdown significantly suppresses tumor growth, while KLF4 knockdown rescues MEX3A inhibition-induced suppression of tumor growth (Figure EV4A-C)." (PMID 36276637, 2022). "To date, there are few reports about the effect of MEX3A on tumor cells." (PMID 35715407, 2022). "Furthermore, Mex3a knockdown promoted cell death in irradiated APKS mouse tumor organoids and led to their slower recovery as compared to control, suggesting that Mex3a silencing sensitizes tumor cells to radiation-induced DNA damage." (PMID 36276637, 2022). "Together, these data suggested that MEX3A promotes tumor growth in vivo." (PMID 35490173, 2022). "Furthermore, the oncogenic functions of Mex3a were further validated when Mex3a was deleted in Vil-Cre;APCfl/+mice, in which APC mutation-driven tumor mouse model is relevant to human familial CRC." (PMID 36276637, 2022). "Notably, MEX3A inhibition not only suppresses proliferative capacity of tumor cells, but also renders tumor cell-state conversion from stemness to differentiation, evidenced by reduction of CD44 and upregulation of E-cadherin." (PMID 36276637, 2022). "Accordingly, increased MEX3A levels could contribute to the repression of the bona fide tumor-suppressive CDX2 in the intestine." (PMID 34067172, 2021). "We have further demonstrated that MEX3A enhanced tumor proliferation and migration in vitro." (PMID 34189143, 2021).
tumor (continued). "In conclusion, our study identified MEX3A as a tumor promotor in ESCC, which may be used as a prognostic indicator and novel therapeutic target in the treatment of ESCC." (PMID 33188661, 2020). "Bioinformatics analysis using the Tumor Cancer Genome Atlas (TCGA) revealed low MEX-3A (p = 0.0026) and low MEX-3C mRNA (p = 0.0089) expression levels in endometrial cancer (no data for testicular germ cell tumors available), which were significantly associated with a better overall survival (OS)." (PMID 32717840, 2020). "Interestingly, the genetic depletion of MEX3A results in the impairment of GB cell proliferation, providing new insights on GB tumor biology and identification of potential and innovative therapeutic approaches." (PMID 32019099, 2020). "In conclusion, MEX3A was identified as a tumor promotor in the development and progression of ESCC by targeting CDK6, which may be considered as a novel prognostic indicator and therapeutic target in treatment of ESCC." (PMID 33188661, 2020). "Interestingly, the expression of MEX3A was higher with increased histological grade (p < 0.0001), suggesting that MEX3A is related to tumor progression." (PMID 31998552, 2020). "We found that MEX3A was upregulated in ESCC tumor tissues and its upregulation or downregulation could promote or suppress the development and progression of ESCC." (PMID 33188661, 2020). "Relationship between MEX3A expression and tumor characteristics in patients with ESCC." (PMID 33188661, 2020). "More importantly, the ability of MEX3A knockdown to restrain tumor growth in vivo suggested that it may be used as novel therapeutic target in the treatment of ESCC." (PMID 33188661, 2020). "In addition, from the western blot results, compared with tumors of shCtrl group, the protein MEX3A expression of shMEX3A group tumor was downregulated." (PMID 32140076, 2020). "To date, a few studies have evaluated the effect of mex3a on tumor cells." (PMID 28903380, 2017). "Moreover, we demonstrate that the inhibition of MEX3A arrests tumor growth in vitro and in vivo." (PMID 40958871, 2025). "Notably, MEX3A knockdown inhibits tumor growth in vitro and in vivo." (PMID 40958871, 2025). "Similarly, MEX3A downregulation in tumor xenografts diminished significantly tumorigenicity suggested that it could be as a new therapeutic target of BC." (PMID 37433992, 2023). "In summary, the results indicate that the sequence and copy number of MEX3 genes were not altered significantly, except for MEX3A overexpression, which revealed that this gene family is stable and not readily mutated, leading to the malignant proliferation of tumour cells." (PMID 36507941, 2023). "Hence, we speculate that MEX3A is extremely important as a prognostic indicator in OC patients and can be used as a predictor of tumor proliferation and metastasis." (PMID 34189143, 2021). "FMRP interacts with both GSK3β and CTNNB1, MSI1 represses APC and enhances Wnt signaling in epithelial progenitors, while MEX3A stabilizes LGR5 and represses DKK1, thereby promoting stemness and tumor progression." (PMID 41516083, 2025). "As expected, in subcutaneous xenograft model, circMPP6 overexpression substantially enhanced the tumorigenicity and tumor growth of CRC cells, which indicates the potential mediator role of circMPP6 for MEX3A." (PMID 38565536, 2024). "The newly discovered crucial roles of MEX3A and IGFBP4 in tumor progression provide theoretical basis of pathogenesis and potential novel strategy for the treatment of BC." (PMID 37433992, 2023). "More importantly, transfection with the miRNA-3163 inhibitor rescued the tumor suppressive effects of MEX3A knockdown in NPC cells (P < 0.05, 0.01 or 0.001), indicating that miRNA-3163 is a downstream regulator of MEX3A." (PMID 35490173, 2022). "Increased expression of MEX3A was correlated with higher disease stage in PDAC patients and with tumor development in a mouse model of PDAC." (PMID 33159833, 2021).
tumor (continued). "We find that MEX3A is strongly up-regulated in GB specimens, and this correlates with very low protein levels of RIG-I, a tumor suppressor involved in differentiation, apoptosis and innate immune response." (PMID 32019099, 2020). "Further verification revealed that, similar with MEX3A, CDK6 was also upregulated in ESCC tumor tissues compared with normal tissues, which was also in consistent with the previous report." (PMID 33188661, 2020). "We further investigated whether MEX3A regulates EMT transition in CRC cells, which plays an important role in tumor metastasis." (PMID 38914858, 2024). "To explore the potential role of MEX3A in BC, we first carried out analyses of non-matched and matched tumor and normal samples in TCGA databases, and found MEX3A was significantly overexpression in BC samples." (PMID 37433992, 2023). "In conclusion, our study demonstrated that MEX3A, a novel carcinogenic RBP in BC, could promote tumor cell progression through mediated IGFBP4 post-transcriptional metabolism, ultimately affecting survival in BC patients." (PMID 37433992, 2023). "Notably, MEX3A depletion led to decreased cell proliferation, invasion, and migration, but increased apoptosis in NPC cells in vitro, while inhibiting tumor growth in vivo." (PMID 35490173, 2022). "Although MEX3A has a key role in gastrointestinal homeostasis and tumor progression, its putative role in neural context is not yet defined." (PMID 33072742, 2020). "In conclusion, targeting MEX3A, either alone or in combination with RIG-I activation, represents a compelling therapeutic strategy that could disrupt GSC-driven resistance, restore anti-tumor immunity, and ultimately shift the treatment paradigm in GB." (PMID 40958871, 2025). "Furthermore, while this work was in progress, another study reported the up‐regulation of MEX3A protein in PDAC patients correlated with poor prognosis, whereas depletion of MEX3A in PDAC cells inhibited proliferation and migration in vitro and tumor development in mouse xenograft model." (PMID 33159833, 2021). "Also, the discrepancies between the tumour size observed after xenografting iSOX11 cells via the mammary fat pad model and the MIND model, as well as the finding that EGF can decrease MEX3A levels, suggest an influence of microenvironmental factors on SOX11 tumour cell behaviour." (PMID 32909943, 2020). "We observed a higher Mex3a promoter methylation level in HCC patients with ascites compared with patients without ascites, which may be because Mex3a can promote tumor progression and affect prognosis." (PMID 39564121, 2024).
infection (1 paper, 2025). The state of being infected such as from the introduction of a foreign agent such as serum, vaccine, antigenic substance or organism. "GB-derived neurospheres from GB samples with different molecular backgrounds were genetically silenced for MEX3A by infection with lentiviral particles encoding two different short hairpins RNA or non-targeting shRNA as control." (PMID 40958871, 2025).
MEX3A also shares sentences with these, for which no sentence is quoted: acute myeloid leukemia (1 paper); atherosclerosis (1); chromophobe renal cell carcinoma (1); Encephalopathy (1); esophageal squamous cell carcinoma (1); heart failure (1); intestinal cancer (1); laryngeal carcinoma (1); melanoma (1); metastasis (1); nasopharyngeal carcinoma (1); non-alcoholic fatty liver disease (1); rectal adenocarcinoma (1).